EPHA6 (EPH receptor A6)
Diseases named in the same sentence as EPHA6 in open-access papers (continued):
Sharing a sentence is not in itself a finding about the gene and the disease.
tumor (13 papers, 2015 to 2025). "These associations suggest a role for EphA6 in regulating neuronal architecture and cellular organization within the tumor microenvironment, potentially influencing migration and tumor progression." (PMID 41200151, 2025). "In their report, shRNA targeting a common region of both full-length and truncated splice variants of EPHA6 seemed to decrease tumor angiogenesis and metastasis to a larger degree, compared with an shRNA that targeted only full length EPHA6." (PMID 29535823, 2018). "EphA4 and EphA6 are implicated in tumor biology of several cancer types." (PMID 34943502, 2021). "In contrast, EphA6 and EphA10 displayed elevated expression in the C3 and C5 subtypes, suggesting a potential tumor-suppressive effect." (PMID 38952552, 2024). "IFNβ-induced exosomal linc-EPHA6-1 reinforces NK cell cytotoxicity against tumor cells and Zika virus infected tumor cells through miR-4485-5p-mediated the increase of NKp46, a vital natural cytotoxicity receptor." (PMID 33148302, 2020). "Investigation of the other genes of possible biological significance in CRC identified that EPHA6 was described as the tumor suppressor gene according to its role in the regulation of angiogenesis process." (PMID 30846004, 2019). "This is consistent with our present data, and suggests that alternative splicing of the EPHA6 gene plays a critical role in tumor growth and metastasis in CRPC." (PMID 29535823, 2018). "The number of cells positive for EphA6 was significantly higher in the primary cancer tissues than in matched adjacent non-tumor tissues." (PMID 26041887, 2015). "EphA6 mRNA expression levels in CaP tumor tissues were significantly higher than in the benign prostate tissues from the BPH patients (P < 0.001)." (PMID 26041887, 2015). "We also observed that EphA6 tumor expression is positively correlated with vascular invasion, neural invasion, PSA and TNM staging in the 112 human CaP cases." (PMID 26041887, 2015). "EphA6 expression is high in CaP tumor tissues while almost undetectable in the adjacent non-tumor tissues." (PMID 26041887, 2015). "Moreover, the expression of PIK3IP1, a negative regulator of PI3K and suppressor of tumor development, increases after EphA6 knock-down." (PMID 26041887, 2015). "In contrast, EphA6 protein was strongly expressed in primary CaP tumor tissues." (PMID 26041887, 2015). "Minimal EphA6 protein was detected in the adjacent non-tumor tissues." (PMID 26041887, 2015). "Furthermore, increased EphA6 expression is detected in 112 CaP tumor tissue samples compared with 58 benign prostate tissues from BPH patients." (PMID 26041887, 2015). "Collectively, these data indicate that knock-down of EphA6 may contribute to the reduced tumor growth and metastasis through the inhibition of tumor neovascularization." (PMID 26041887, 2015). "Considering that the Eph family has been reported to be involved in angiogenesis, we next investigated whether the suppression of tumor growth and metastasis by knock-down of EphA6 was due to decreased angiogenesis, at least partially." (PMID 26041887, 2015). "Further, EphA6 knock-down decreased the microvascular density (MVD), an indicator of angiogenesis, in PC-3M/shEphA6-1 or PC-3M/shEphA6-2 tumor tissues compared with PC3-M/shControl." (PMID 26041887, 2015). "Our study indicates that knock-down of EphA6 slows primary tumor growths, but did not affect cell proliferation rates in vitro, suggesting that knock-down of EphA6 mediated decrease in tumor growth is not due to changes in the proliferation rates of tumor cells." (PMID 26041887, 2015). "To investigate whether the results observed in CaP cell lines also hold true in clinical samples, we assessed EphA6 protein expression in 25 pairs of primary CaP tumor tissues and matched adjacent non-tumor tissues by immunohistochemistry." (PMID 26041887, 2015). "These intriguing results suggest that EphA6 may affect cells in the tumor environments rather than the proliferation of the tumor cells." (PMID 26041887, 2015).
cancer (10 papers, 2013 to 2025). A tumor composed of atypical neoplastic, often pleomorphic cells that invade other tissues. "Cancer-associated fibroblasts (CAFs), marked by Col1a1, Cdh2, Epha6, and Prkch, were classified into two subtypes (CAFs 1 and 2)." (PMID 40723284, 2025). "This is the case of ephrin type-A receptor 6 (EPHA6), which encodes a tyrosine kinase receptor that exerts complex activities in cancer and is consistently overexpressed in metastatic PCa cells." (PMID 38493226, 2024). "The results emphasize the marked elevation in expression for the majority of EphA genes among cancer patients, except for EphA5, EphA6, and EphA8." (PMID 38952552, 2024). "Epithelial-rich subtypes showed higher EphA6 cytoplasmic H-score (B2/B3, carcinoma) (p < 0.001) and stronger EphA4 H-score (B3, carcinoma) (p = 0.011)." (PMID 34943502, 2021). "Although further mechanistic investigation into the regulation of metastasis by EphA6 is necessary, the observed pro-metastatic activity of EphA6 in CaP supports EphA6 to be a potential target for cancer metastasis therapy." (PMID 26041887, 2015). "Similarly, low expressions of CYTH3, NOVA1, and EPHA6 were highly correlated with longer OS in patients with other types of cancers." (PMID 36506313, 2022). "Further, genome-wide gene expression analysis in EphA6 knock-down cells identified a panel of differentially regulated genes including PIK3IPA, AKT1, and EIF5A2, which could contribute to EphA6-regulated cancer progression." (PMID 26041887, 2015).
psychiatric disorder (1 paper, 2017). A disorder characterized by behavioral and/or psychological abnormalities, often accompanied by physical symptoms. "Ten genes were enrichedwith several KEGG pathways, and ROBO2, CXCL2, EPHA5,EPHA6, ANGPT2, FGF10, GHF genes was found to be enrichedwith pathways influencing psychiatric disorders like Axonguidance, RAP1 Signaling pathways, RAS Signaling pathwaysetc." (PMID 28539732, 2017).
EPHA6 also shares sentences with these, for which no sentence is quoted: urinary tract infection (2 papers); autism (1); autism spectrum disorder (1); brain tumors (1); candidiasis (1); co-infection (1); colorectal tumors (1); diabetic nephropathy (1); familial Alzheimer disease (1); gestational diabetes (1); kidney transplant (1); neurodevelopmental disorder (1); retinal degeneration (1); thymic epithelial tumors (1); uveal melanoma (1).